XPC (XPC complex subunit, DNA damage recognition and repair factor)
Diseases named in the same sentence as XPC in open-access papers (continued):
Sharing a sentence is not in itself a finding about the gene and the disease.
bladder cancer (26 papers, 2005 to 2025). "This study demonstrates that XPC deficiency in bladder cancer cells can promote autophagy in response to the cisplatin-mediated DNA damage response (DDR)." (PMID 41215711, 2025). "Some researchers have shown that XPC 1496C>T is associated with the risk of breast cancer and bladder cancer." (PMID 38541232, 2024). "Overall, these studies support a role of XPC expression in variable risk and outcomes of bladder cancer, although the exact mechanisms of epigenetic regulation, and the specific mechanisms by which risk is altered in low XPC, remains less clear." (PMID 35530314, 2022). "Several rare XPC mutations, identified in patients with bladder cancer, were studied in vitro and were associated with decreased XPC mRNA and protein expression." (PMID 35530314, 2022). "In this, as in several other cancers, XPC polymorphisms were associated with low penetrance susceptibility to bladder cancer." (PMID 35530314, 2022). "Recently, SNP rs2228001 of the XPC gene has been extensively investigated for its association with carcinogenesis of some tumor types (i.e., cancers of the bladder, lung, and colorectum); however, the findings were inconclusive with PCa." (PMID 27974699, 2017). "An independent study showed the same XPC gene variant is associated with cisplatin induced neutropenia and hematological toxicity in adult patients treated for bladder cancer." (PMID 27618021, 2016). "In conclusion, XPC Ala499Val substitution increases urinary bladder cancer risk, but Lys939Gln appears to be neutral." (PMID 27246180, 2016). "Previous studies have demonstrated that XPC deficiency is an important contributing factor in bladder tumor progression and bladder cancer cell drug resistance." (PMID 27246180, 2016). "The associations of attenuated XPF/XPC expression with tumor grade and the patients' smoking status in 219 patients with bladder cancer." (PMID 25535740, 2014). "Compared with He J’s work, we only focused on the association of XPC polymorphisms with lung cancer, while He J and colleagues analyzed a variety of cancers, including lung cancer, breast cancer, bladder cancer, colorectal cancer, etc." (PMID 24736739, 2014). "A total of 12 studies with 4828 cases and 4890 controls for evaluating the XPC Lys939Gln polymorphism and urinary bladder cancer were included." (PMID 23819639, 2013). "This meta-analysis, including 4,828 cancer cases and 4,890 controls from 12 published case–control studies, explored the association between the XPC Lys939Gln polymorphism and bladder cancer risk." (PMID 23819639, 2013). "The overall results indicated that there were significant associations between all three studied XPC Lys939Gln polymorphism and increased risk of bladder cancer." (PMID 23819639, 2013). "Overall, we found that there was evidence that the variant genotypes of the XPC Lys939Gln were associated with a significant increased overall risk of bladder cancer." (PMID 23819639, 2013). "Our meta-analysis suggested that the XPC Lys939Gln polymorphism contributed to the risk of urinary bladder cancer." (PMID 23819639, 2013). "Polymorphisms in XPC gene have been evaluated as risk factors in bladder cancer in a number of epidemiological studies, however the conclusions were controversial." (PMID 23819639, 2013). "The results of our HDAC inhibition study revealed that the treatment of HTB4 and HTB9 bladder cancer cells with the HDAC inhibitor valproic acid (VPA) caused an increase in transcription of the XPC gene in these cells." (PMID 21507255, 2011). "XPC is involved in the nucleotide excision repair of DNA damaged by carcinogens known to cause bladder cancer." (PMID 21689419, 2011). "Garcia-Closas evaluated the influence of common genetic variation in the NER pathway on bladder cancer risk by analyzing 22 single nucleotide polymorphisms (SNP) in seven NER genes (XPC, RAD23B, ERCC1, ERCC2, ERCC4, ERCC5, and ERCC6)." (PMID 19055767, 2008).
bladder cancer (continued). "XPC deficiency has also been associated with inhibition of BRCA1 expression on bladder cancer cells treated with cisplatin, resulting in accumulation of DNA damage and pointing to a potential indirect role of XPC in homologous recombination or, more likely, replication-induced double strand breaks." (PMID 35530314, 2022). "XPC methylation was associated with the malignant behavior of bladder cancer and may predict poor prognosis." (PMID 26967246, 2016). "However, a study with the larger sample size is needed to further evaluated gene-environment interaction on XPC Lys939Gln polymorphism and bladder cancer risk." (PMID 23819639, 2013). "In conclusion, this meta-analysis indicates that XPC Lys939Gln polymorphism may be contributed to the development of bladder cancer risk." (PMID 23819639, 2013). "Overall, there was significant associations between the XPC Lys939Gln polymorphism and urinary bladder cancer risk were found for homozygous model (OR = 1.352, 95% CL = 1.088-1.681), heterozygous model (OR = 1.354, 95% CL = 1.085-1.688), and allele comparison (OR = 1.109, 95% CL = 1.013-1.214)." (PMID 23819639, 2013). "We therefore hypothesised that the two 3'UTR SNPs might have an effect on XPC mRNA stability and/or reduced mRNA transcription and/or translation, which could explain the association of c.1496T and increased bladder cancer risk." (PMID 21689419, 2011). "Individuals homozygous for the variant allele of XPC c.1496C > T (p.Ala499Val) were shown in a large pooled analysis to have an increased bladder cancer risk, and we found two 3'UTR variants, *611T > A and c.*618A > G, to be in strong linkage disequilibrium with c.1496T." (PMID 21689419, 2011). "The XPC SNP c.1496C > T (p.Ala499Val) is associated with increased bladder cancer risk." (PMID 21689419, 2011). "Valproic acid administration in T24 and 5637 bladder cancer cells induced transcription of XPC gene, while prior treatment of these cells with valproic acid enhanced cisplatin-induced activation of caspase-3." (PMID 30875794, 2019). "We analyzed polymorphisms in the Xeroderma Pigmentosum, Complementation Group C (XPC) gene for their correlation with urinary bladder cancer." (PMID 27246180, 2016). "Attenuated expression of the DNA damage response protein Xeroderma Pigmentosum complementation group C (XPC) has been described in bladder cancer." (PMID 25927440, 2015). "We optimized conditions for dissociation and in vitro culture of primary bladder cancer cells and confirmed attenuated XPC expression in approximately 40% of the tumors." (PMID 25927440, 2015). "Our study is the first one to describe the correlation between functional NER activity and XPC protein levels measured directly in primary bladder cancer." (PMID 25927440, 2015). "The study results suggested that two NER genes, XPF and XPC, were involved in the relapse of bladder cancer." (PMID 25535740, 2014). "This suggests that XPF and XPC are both related with the relapse of bladder cancer and involved in several cellular response pathways." (PMID 25535740, 2014). "Despite our study showing that XPF, XPC and smoking were closely related with the relapse of bladder cancer, the reason for low expression of XPF and XPC was still unclear." (PMID 25535740, 2014). "All of these results suggest that the HDACs negatively regulate transcription of the XPC gene in bladder cancer cells and contribute to the severity of bladder tumors." (PMID 21507255, 2011). "Recent studies demonstrate reduced levels of XPC protein in tumors for a majority of bladder cancer patients." (PMID 21507255, 2011). "This provides an important basis for understanding the mechanism of XPC gene silencing in bladder cancer cells." (PMID 21507255, 2011). "In this work we investigated the role of histone deacetylases (HDACs) in XPC gene silencing and bladder cancer development." (PMID 21507255, 2011).
bladder cancer (continued). "The work described in this study was mainly focused on determining the role of HDACs in XPC gene silencing and bladder cancer development." (PMID 21507255, 2011). "In this work we have determined the role of HDACs in XPC gene silencing and bladder cancer development." (PMID 21507255, 2011). "In this study, we focused on determining the role of histone deacetylases (HDACs) in XPC gene silencing and bladder cancer development." (PMID 21507255, 2011). "Recent studies have demonstrated linkage disequilibrium between three polymorphisms in the XPC gene (polyAT, IVS11-6 and Lys939Gln) and these have been shown to influence the DRC, as well as to be associated with bladder cancer risk." (PMID 15886698, 2005). "We analysed all three XPC polymorphisms in 547 bladder TCC patients and 579 cancer-free controls to investigate the association between these polymorphisms and bladder cancer susceptibility, and we also attempted to assess gene–environmental interactions." (PMID 15886698, 2005). "Supporting their likely role in bladder cancer development, XPC mRNA and protein expression is decreased in bladder cancer tumors and may portend a worse prognosis." (PMID 35530314, 2022). "XPC, as a nucleotide excision repair gene, is related to the occurrence of various cancers, such as colorectal cancer, prostate cancer, lung cancer, breast cancer, and bladder cancer." (PMID 34803670, 2021). "For example, XPC rs2228000 was reportedly related to susceptibility to bladder cancer cases in Iraq, Sweden, or India but not the U.S.A. or Spain." (PMID 31710080, 2019). "We conclude, that (i) functional NER deficiency is a relatively rare phenomenon in bladder cancer and (ii) XPC protein levels are not useful as biomarker for NER activity in these tumors." (PMID 25927440, 2015). "XPC expression levels compared to UDS levels in bladder cancer." (PMID 25927440, 2015). "However, the fact that XPF and XPC are involved in the relapse of bladder cancer brings a new reliable clue for further studies on the mechanism of bladder cancer relapse." (PMID 25535740, 2014). "Decreased XPF and XPC expression in 79 patients of human bladder cancer." (PMID 25535740, 2014). "To confirm this hypothesis, we analyzed the connection between the expression levels of XPC in tumor tissues of 219 bladder cancer patients and their prognosis and found XPC (−) patients had a significantly higher relapse rate." (PMID 25535740, 2014). "Because of the important function of XPC protein in the cisplatin-caused apoptosis and the role HDACs in XPC gene silencing, we further investigated the effect of the HDAC inhibitor VPA in cisplatin-induced apoptosis of bladder cancer cells." (PMID 21507255, 2011). "To further determine the role of HDACs in XPC gene silencing and bladder cancer development, we determined the correlation between the presence of HDACs and the occurrence of bladder cancer using bladder tumor tissue arrays with an immunohistochemistry (IHC) staining procedure." (PMID 21507255, 2011). "In order to determine the role that the HDACs may play in XPC gene silencing and bladder cancer development, we first determined the effect of HDAC inhibitor treatment on activation of XPC gene transcription in HTB4 and HTB9 bladder cancer cells." (PMID 21507255, 2011). "The mechanism that leads to reduced levels of XPC protein in the tumors of bladder cancer patients is unknown." (PMID 21507255, 2011). "Using HTB4 (T24) and HTB9 bladder carcinoma cells, the results of our HDAC inhibitor studies demonstrated that treatment with a HDAC inhibitor, valproic acid (VPA), caused increased transcription of the XPC gene in these cells." (PMID 21507255, 2011). "All of these results suggest that over-expression of the HDAC4 contributes to the XPC gene silencing and the development of bladder carcinomas, and inhibiting the HDAC activities with the HDAC inhibitor VPA sensitizes the bladder carcinoma cells to anticancer drug cisplatin." (PMID 21507255, 2011).
bladder cancer (continued). "Polymorphisms in the XPC gene may alter NER capacity, thus giving rise to genetic predisposition to bladder cancer." (PMID 15886698, 2005). "The selected variants XPC 1496C>T, XPC 2920A>C, XPD 2251A>C, XPF-673C>T, XPF 11985A>G, and XPG 3507G>C were studied in different populations for multiple types of cancers: breast cancer, bladder cancer, ovarian cancer, hematological diseases such as Hodgkin’s Lymphoma, PV and ET, AML, and CML." (PMID 38541232, 2024). "Hence, XPC protein might be an informative biomarker to guide personalized therapy strategies in a subset of bladder cancer cases." (PMID 25927440, 2015). "It suggests that the reduced XPC may be involved in the relapse of bladder cancer." (PMID 25535740, 2014). "Moreover, the proportion of XPC (−) was correlated with the pathological grading of bladder cancer." (PMID 25535740, 2014). "In addition, the results obtained from these studies further suggests that reactivation of the XPC gene by HDAC inhibitors may have great benefits for bladder cancer treatment, especially for DNA-damaging anticancer drugs such as cisplatin." (PMID 21507255, 2011). "Therefore, future studies also need to determine the roles of these epigenetic regulation mechanisms in XPC gene silencing and bladder cancer development in order to provide a better understanding of the mechanism of XPC gene silencing and bladder cancer development." (PMID 21507255, 2011). "Determination of the level of XPC gene 5' regulatory region DNA co-precipitated with the transcription factors CREB1 and Sp1 by IP in both untreated and VPA-treated HTB4 and HTB9 bladder cancer cells a." (PMID 21507255, 2011). "The effect of valproic acid (VPA) treatment on transcription of XPC and XPA genes in both HTB4 and HTB9 bladder cancer cells." (PMID 21507255, 2011). "The results obtained from our HDAC inhibitor treatment studies revealed that the VPA treatment led to an increase in transcription of the XPC mRNA in both HTB4 and HTB9 bladder cancer cells." (PMID 21507255, 2011). "XPC is a DNA-damage recognition protein required for the initiation of the nucleotide-excision repair (NER) process and reduced levels of XPC protein have been reported in tumors derived from bladder cancer patients." (PMID 30875794, 2019). "However, XPC may play a role that is independent of its direct function related to UV-damage, as evidenced by the association of epigenetic silencing of XPC with shorter survival in bladder cancer." (PMID 31382494, 2019). "Our results suggest that XPF and XPC expression may be a potential predictive factor for bladder cancer, and smoking can not only influence the recurrence of bladder cancer as a single factor but also aggravate the results of the XPF defect and XPC defect." (PMID 25535740, 2014). "However, as for the replace of bladder cancer, XPF and XPC play their roles in the same mechanism, the NER mechanism, but not in different mechanisms." (PMID 25535740, 2014). "We found the expressions of the NER gene XPF and XPC were significantly lower in bladder cancer tissues with a recurrence compared with those without a recurrence at mRNA level." (PMID 25535740, 2014). "Although the low expression of XPF and XPC was involved in the relapse of bladder cancer, the comprehensive analysis found that there was no synergic enhancement effect between the reduced expression of XPF and XPC." (PMID 25535740, 2014). "Thus, ATR and XPC are involved in UV-induced JNK signaling, which regulate the expression of pol ι in normal cells and bladder cancer cells." (PMID 23922701, 2013). "We found XPC was Attenuated expressed in relapsed bladder cancer than non-relapsed bladder cancer." (PMID 25535740, 2014).
lung carcinoma (24 papers, 2007 to 2025). "Low XPC expression is associated with decreased overall survival in lung cancer patients, according to a public database Kaplan–Meier analysis." (PMID 40157540, 2025). "XPC is downregulated in lung adenocarcinoma patients, and downregulation of XPC in lung cancer cells is associated with increased expression of cancer stem cell biomarkers and cell invasive capacity." (PMID 40157540, 2025). "Evidence shows that XPC polymorphisms are associated with the different capacity to repair DNA damage and further impact the individual's susceptibility to lung cancer." (PMID 35991047, 2022). "XPC rs2733533 associated with lung cancer susceptibility, the combination of genotype A carriers and heavy smokers (≥30 pack-year) had a 13.32-fold risk of lung cancer compared with the C/C genotype and no smoking." (PMID 35530314, 2022). "Germline mutations causing XP-C are rare, however, more common XPC polymorphisms and variations in gene expression have been studied in lung cancer." (PMID 35530314, 2022). "Mechanistically, XPC deficiency has been reported to increase the invasiveness of lung cancer through downregulation of p27 (kip) and upregulation of skp2 and E2F1." (PMID 25871391, 2015). "XPC knockout mice are highly predisposed to UV radiation-induced skin cancer, as well as 2-acetylaminofluorene-induced liver and lung cancer." (PMID 25871391, 2015). "While the present meta-analysis is under review, Zhu ML reported another meta-analysis about XPC polymorphism and lung cancer risk." (PMID 24736739, 2014). "It is reported that several common polymorphisms of XPC are associated with susceptibility to lung cancer." (PMID 24736739, 2014). "In this meta-analysis, we identified 14 eligible studies, including 5647 lung cancer cases and 6908 controls, and analyzed the relationship between XPC Lys939Gln, Ala499Val, and PAT polymorphisms and susceptibility to lung cancer." (PMID 24736739, 2014). "In this hospital-based case-control study, we investigated five XPC tagging, common single nucleotide polymorphisms (tagging SNPs) in 1,010 patients with newly diagnosed lung cancer and 1,011 matched cancer free controls in a Chinese population." (PMID 17498315, 2007). "In this large-scale case-control study, we investigated the associations between five tagging SNPs of the DNA repair gene XPC and risk of lung cancer in a Chinese population." (PMID 17498315, 2007). "Although the XPC protein is known to play an important role in the NER pathway, the results of published association studies on XPC SNPs and risk of lung cancer remain inconsistent." (PMID 17498315, 2007). "In a previous report, we have shown that individuals homozygous for the XPC PAT polymorphism have an increased risk of developing lung cancer." (PMID 17705814, 2007). "To further investigate the association between the XPC gene and risk of lung cancer in Chinese populations, we took a different approach." (PMID 17498315, 2007). "The expression of P21 and XPC is negatively associated with CUL4A in lung cancer." (PMID 32587774, 2020). "However, the mechanisms linking loss of XPC expression and poor prognosis in lung cancer are still unclear." (PMID 25871391, 2015). "Thus, we performed this update meta-analysis to provide more precise estimation of the relation between XPC polymorphisms and susceptibility to lung cancer." (PMID 24736739, 2014). "Additionally, the XPC intronic poly-AT insertion/deletion polymorphism (PAT) was also associated with lung cancer risk in Caucasians." (PMID 24736739, 2014). "When we analysed the association between XPC genotypes and lung cancer risk, we found that those individuals homozygous for the PAT+ allele presented a not statistically significant higher risk of lung cancer (adjusted OR = 1.28; 95% CI = 0.85–1.92, P = 0.229)." (PMID 17705814, 2007). "In summary, this study provided further evidence that the XPC genotypes and haplotypes may contribute to susceptibility to lung cancer." (PMID 17498315, 2007).